IL24 (interleukin 24)
Diseases named in the same sentence as IL24 in open-access papers (continued):
Sharing a sentence is not in itself a finding about the gene and the disease.
tumor (continued). "Irradiated tumor cells infected with LX/IL-24 showed stable IL-24 expression." (PMID 31338417, 2019). "IL-24 and IL-32 are members of cytokine family both serving as tumor suppressor." (PMID 29471827, 2018). "In one study it was demonstrated that overexpression of the miRNA, miR205 in KB oral cell lines induces tumour suppression by up-regulating the cytokine Interleukin-24, (IL-24; known to exhibit tumour-suppressing functions) directly by targeting its promoter binding site." (PMID 27965463, 2017). "IL24, also known as melanoma differentiation-associated gene-7 (MDA-7), is a member of the IL10 cytokine family, and has been identified as an important immune mediator as well as a tumor suppressor." (PMID 28109288, 2017). "Induction of IL-24 seemed to be restricted to the RNA level and was not confirmed by enzyme-linked immunosorbent assay (ELISA) analysis of tumour explant supernatants (SNs)." (PMID 28300057, 2017). "In addition, secreted IL-24 protein induces a robust expression of endogenous IL-24 and subsequent induction of tumor-specific killing through an ER stress-mediated pathway as well as by ROS production." (PMID 27271601, 2016). "Our results showed that HUMSCs infected by Ad-hTERTp-IL24 followed by LentiR.E1A infection could specifically migrate to HepG2 tumor cells and support adenoviral replication in vitro and in vivo 36 h after LentiR.E1A infection." (PMID 27322080, 2016). "Several studies revealed that MDA-7/IL-24 plays a key role in tumor inhibition." (PMID 27931220, 2016). "Previous studies have shown that ZD55 carrying the IL24 gene could selectively replicate in tumor cells and inhibit cell growth more effectively than ONYX-015 and a replication-defective adenovirus carrying the IL24 gene." (PMID 27528029, 2016). "Numerous investigations, including expression profiling in patients’ cells and in vitro and animal experiments, suggest that IL-24’s functions of which includes antibacterial responses, tissue remodeling, wound healing, and anti-tumor effects, require different heterodimeric receptors." (PMID 27271601, 2016). "Overall, we can consider IL-24 as an immunoregulatory cytokine and as an antitumor molecule with a broad range of activities including, cancer-specific induction of apoptosis and inhibition of tumor angiogenesis." (PMID 27271601, 2016). "Induction of IL-24 expression in the tumor cells markedly reduced HMGA1 mRNA and protein levels." (PMID 27602961, 2016). "Although direct injection of recombinant IL-24 or viral-based deliveries are possible, an appealing direction is to identify novel drugs that can upregulate or stabilize endogenous levels of this cytokine tumor suppressor." (PMID 26460950, 2015). "Furthermore, AAV-mediated combined treatment of IL-24 and apoptin significantly reduces tumor growth and induces apoptosis of cancer cells in nude xenograft mice." (PMID 25590298, 2015). "Thus, any anti-tumor activity observed against H1299 cells would be solely attributable to the exogenous IL-24 that is expressed intracellularly when induced by DOX and not confounded by secreted IL-24." (PMID 26009991, 2015). "In this study, we investigated whether phosphorylation of IL-24 is critical for anti-tumor activity." (PMID 26009991, 2015). "Exogenous IL-24 expression was shown to inhibit tumor cell viability." (PMID 26009991, 2015). "In this compound transgenic model, tumor onset was delayed by the presence of MDA-7/IL-24." (PMID 26474456, 2015). "Importantly, MDA-7/IL-24 also inhibited tumor growth of distant untreated tumors in the same athymic mouse, indicating MDA-7/IL-24 also had “bystander” anti-tumor activity." (PMID 26474456, 2015). "Additionally using a pre-existing tumor model by implanting lineage-depleted tumor cells isolated from MMTV-rtTA:IL24tet-on:MMTV-Her2/neu they show that MDA-7/IL-24 expression following doxycycline treatment significantly inhibited pre-existing tumor growth." (PMID 26474456, 2015).
tumor (continued). "We next investigated whether IL-24 could inhibit SDF-1-induced tumor cell migration and suppress the CXCR4 signaling pathway." (PMID 25775124, 2015). "In order to evaluate both the tumor suppressive effects of MDA-7/IL-24 as well as the “bystander” anti-tumor effect of MDA-7/IL-24, approximately 50% of the tumors that formed were injected with the respective virus, while the remaining 50% were left uninjected." (PMID 26474456, 2015). "In principle, D-MBs coupled with the UTMD approach will provide an effective means of releasing the CTV-m7 payload specifically at the tumor region following sonoporation leading to oncolysis at the site of direct infection and mda-7/IL-24-induced cell death in adjacent and distant tumor cells." (PMID 25926554, 2015). "Additionally, combination therapy of IL-24 with SJA5 was more effective in inhibiting tumor cell migration compared to combination therapy of IL-24 and AMD3100 (P<0." (PMID 25775124, 2015). "Furthermore, the “potent bystander apoptosis-inducing effect” is one of the anti-tumor properties of IL-24." (PMID 26361755, 2015). "Finally, we assessed the role of MDA-7/IL-24 in immune regulation, which can potentially contribute to tumor suppression in vivo." (PMID 26474456, 2015). "Alternatively, combining mda-7/IL-24 with a second therapeutic agent that may directly target the tumor, activate the immune system and/or affect the tumor microenvironment might promote a more sustained therapeutic response." (PMID 26460950, 2015). "Hence, we confirm that tumor cells’ growth was inhibited in the IL-24 group and the IL-24 combining with 3-MA group." (PMID 26361755, 2015). "This might be because we were able to control tumor development by xenografting mouse PDX tumor cells after MDA-7/IL-24 expression was present in the mammary glands." (PMID 26474456, 2015). "But AdLTR2EF1α-IL-24 combining with 3-MA influenced the cell cycle of tumor cells strongly." (PMID 26361755, 2015). "MDA-7/IL-24 expression also inhibited tumor development in athymic xenograft mouse models." (PMID 26474456, 2015). "Furthermore, combination treatment of SJA5 with IL-24 showed the highest inhibitory activity on tumor cell migration when compared to all other treatment groups including AMD3100 plus IL-24 treatment (P< 0.05)." (PMID 25775124, 2015). "The authors suggest that phosphomimetic MDA-7/IL-24 or pharmacological induction of phosphorylation of endogenous or exogenous MDA-7/IL-24 may further promote its anti-tumor effects." (PMID 26460950, 2015). "Next we determined whether MDA-7/IL-24 expression could suppress growth of pre-existing tumor cells in vivo." (PMID 26460950, 2015). "The apoptotic pathways by which MDA-7/IL-24 kills tumor cells remain to be fully understood; however, current evidence suggests an inherently high degree of complexity and an involvement of proteins important for the onset of growth inhibition and apoptosis, including Bcl-XL, Bcl-2 and Bax." (PMID 24527085, 2014). "Treatment of lung tumor xenograft with Ad-IL24 resulted in tumor growth inhibition that was associated with reduction in number of CD31 positive endothelial cells, a marker indicative of reduced blood vessels in the tumor." (PMID 24377906, 2013). "Additionally, it was demonstrated that IL-24 protein utilized its receptors for mediating the antitumor activity in tumor cells." (PMID 24377906, 2013). "i) Clinical correlation suggesting IL-24 is a tumor suppressor." (PMID 24377906, 2013). "Additional studies have confirmed IL-24 protein-mediated tumor cell killing." (PMID 24377906, 2013). "ii) Early preclinical study demonstrating IL-24 is a potential tumor suppressor." (PMID 24377906, 2013).
tumor (continued). "The results from this study concurred with our own findings and suggested IL-24 could also indirectly inhibit tumor angiogenesis by reducing growth factor expression by tumor cells." (PMID 24377906, 2013). "Additionally, inhibition of contralateral tumors was demonstrated establishing the concept of IL-24 protein can suppress tumor growth by exerting a “bystander effect”." (PMID 24377906, 2013). "Finally, does post-translational modification (PTM) play a role in the IL-24 protein attaining different functional properties such as tumor suppressor function versus cytokine function and also affect intracellular localization?" (PMID 24377906, 2013). "Additionally, expression of exogenous IL-24 protein was observed in areas of tumor tissues that were outside and beyond Ad-IL24 injection site suggesting IL-24 protein was secreted that diffused throughout the tumor." (PMID 24377906, 2013). "However, these inhibitory effects on HUVEC cells were abrogated on exogenous addition of recombinant VEGF protein to the tissue culture media obtained from Ad-IL24-treated tumor cells." (PMID 24377906, 2013). "However, studies are yet to unravel the intracellular signaling triggered by IL-24 directing tumor cells to undergo cell death versus those mediated by IL-19 and IL-20 that do not trigger tumor cell death." (PMID 24377906, 2013). "Thus, IL-24 suppresses angiogenesis by inhibiting the expression of growth factors produced by tumor cells." (PMID 24377906, 2013). "However, the CTGVT with only one gene still can’t very easily to eradicate all the xenograft tumor with the exception of IL-24 gene which has the excellent anti-tumor effect." (PMID 23675261, 2012). "Since IFNs promote the activity of STAT1 andSOCS1, but inhibits the activity of STAT3, it is theoretically feasible thatIFN-α and IL-24 may augment their anti-tumor activities." (PMID 22569271, 2012). "Designed using predictive computer modeling, SM7L incorporates the therapeutic activity of the promising anti-tumor cytokine MDA-7/IL-24, an enhanced secretory domain, and diagnostic domain for non-invasive tracking." (PMID 22808125, 2012). "Repression of MDA-7/IL-24 expression by TLS–CHOP is required for MLS tumour growth, and TLS–CHOP may become a promising therapeutic target for MLS treatment." (PMID 22588557, 2012). "Therefore, IL-24 is an excellent anti-tumour gene which compare with two gene in the CTGVT-DG strategy and completely eradicate the xenograft tumor." (PMID 23675261, 2012). "Moreover, MDA-7/IL-24 induced potent “bystander antitumor” activity, an ability to block tumor angiogenesis, synergy with radiation, chemotherapy, monoclonal antibody therapies and immune modulatory activity, which make it a ideal tool for cancer gene therapy." (PMID 22629368, 2012). "Wild-type-MDA-7/IL-24 monomers aggregate to form dimers, which then bind and activate defined molecular pathways downstream of IL-20Rα/β receptors to inhibit tumor cell proliferation and survival." (PMID 22808125, 2012). "IL-24 mediates anti-tumor activity reducingSTAT3 expression, which suggests that interferon (IFN) alpha may augmenttumor cell lysis and reduce angiogenesis." (PMID 22569271, 2012). "The notable effectiveness of IL‐24‐based combination therapy regimens stems from the ability of combined therapies to concurrently target multiple key pathways contributing to tumor heterogeneity, thus countering resistance that may arise from individual therapies." (PMID 40338095, 2025).
tumor (continued). "Furthermore, flow cytometric analysis of tumor-infiltrating lymphocytes revealed that Vin-induced increases in CD8+ T cell infiltration, as well as the proportions of GZMB+ and IFNγ+ CD8+ T cells, were abolished in both ATF3- and IL-24-deficient tumors." (PMID 40866941, 2025). "This anti‐tumor response elicited by IL‐24 administration largely involved the activation and infiltration of CD8+ T cells accompanied by the release of pro‐inflammatory cytokines such as TNF, IL‐1, IFN‐γ, and IL‐12, although the precise mechanism behind these effects remains largely unknown." (PMID 40338095, 2025). "Finally, in a clinical setting involving intra‐tumoral administration of adenovirus expressing IL24 (INGN‐241) to cancer patients, greater tumor cell apoptosis was observed at the tumor site and distant sites, underscoring the pronounced bystander effect of IL‐24 in humans." (PMID 40338095, 2025). "Interestingly, RNA‐sequencing analysis showed that IL24 may enhance iNK cell function through nuclear factor kappa B (NFκB) pathway‐related genes while exerting a direct effect on tumor cells." (PMID 38737469, 2024). "The results from tri-modality system further confirm that B.breve-IL-24 could offer a novel, safe, and clinically acceptable therapeutic approach for tumor therapy in vivo, which might contribute to preoperative prediction and intraoperative monitoring of tumors." (PMID 35814447, 2022). "Additionally, these findings suggest that VV-IL-24 paired with luteolin had a higher anti-tumor efficiency in vivo, and the pairing may have contributed to increased IL-24 gene expression as well as the prevention of tumor cell proliferation and angiogenesis." (PMID 36146619, 2022). "Since WT1 and IL-24 are rarely expressed in KIRC tissues, we investigated the clinical prognostic significance of WT1-regulated genes, including GDD45A and TXNIP, finding that the levels of these genes were associated with the histological grade, tumor stage, and metastasis in KIRC patients." (PMID 35915803, 2022). "An increased tumor inhibition (including tumor growth and tumor cell apoptosis) was observed in the treatment group compared to the control groups, which further confirmed the therapeutic effect of a new IL-24-expressing strain gene therapy on the tumor in vivo." (PMID 35814447, 2022). "Thus, the decrease in IL24 is probably a measure of reduction of the tumor mass." (PMID 34944584, 2021). "In addition, many studies have shown that IL24 mRNA can be used as a potential tumor treatment." (PMID 33014054, 2020). "A previous study showed that tumor cells modified with a replication-deficient adenovirus expressing IL-24 can enhance the antitumor immune responses, while using nonlytic NDV as a vector to transfer IL-24 to tumor cells is superior to using replication-deficient adenovirus." (PMID 31338417, 2019). "Effects were additive for ING4 and IL-24, and in addition up-regulation of the tumor suppressors p21, p27, fas cell surface death receptor (Fas), Bax, and the apoptosis-promoting cleaved caspases-8, -9, -3, and down-regulation of the tumor-promoter Bcl-2 apoptosis regulator (Bcl-2) was observed." (PMID 31390718, 2019). "Next, we examined the therapeutic effects of LX/IL-24-modified tumor vaccines, and significant inhibition of tumor growth was observed after being treated with LX/IL-24-modified tumor vaccines, indicating the production of IL-24 by NDV-infected vaccine cells may enhance antitumor effects." (PMID 31338417, 2019).
tumor (continued). "In addition, understanding the mechanism in which IL-24 mRNA is stabilized could lead to the development of therapeutic strategies that prolong IL-24 mRNA half-life enabling enhanced killing in tumor cells." (PMID 30669553, 2019). "Ad-hTERTp-IL24 specifically inhibited HepG2 cells growth, and this inhibitory effect was enhanced by low doses of 5-fluorouracil (5-Fu), because the expression levels of coxsackie adenovirus receptor (CAR) and integrin ανβ3 on tumor cells were significantly increased, causing higher viral uptake." (PMID 27322080, 2016). "Thus, induction of exogenous mda-7/IL-24 may not only suppress cell proliferation directly but may also elicit an immune response in immune-competent animals, further attenuating tumor growth." (PMID 26460950, 2015). "Despite initial growth suppression, tumors in triple compound transgenic mice lost mda-7/IL-24 expression and grew, albeit after longer latency, indicating that continuous presence of this cytokine within tumor microenvironment is crucial to sustain tumor inhibitory activity." (PMID 26460950, 2015). "However, in the IL-24 group and the combination group tumor cells’ growth was inhibited." (PMID 26361755, 2015). "Furthermore, injection of IL-24-MSCs significantly suppressed xenograft tumor growth in mice." (PMID 25590298, 2015). "These initial studies demonstrating IL-24 is a novel tumor suppressor/cytokine gene provided the impetus for conducting large scale studies testing IL-24 as an anticancer drug and unraveling the molecular mechanisms by which IL-24 exerted its antitumor activities." (PMID 24377906, 2013). "Moreover, conditioned tissue culture supernatant obtained from Ad-IL24 treated tumor cells when added to actively growing HUVEC cells markedly diminished VEGF receptor 2 (VEGFR2)-mediated AKT signaling that resulted in induction of endothelial cell growth arrest and apoptosis." (PMID 24377906, 2013). "Our mRNA and protein expression measurements weretherefore designed based on IFN-α signaling and did not include an IL-24 group.Our goal was to understand if combining IFN-α with IL-24 could enhanceanti-tumor activity via inhibition of STAT3 to promote anti-angiogenic effects." (PMID 22569271, 2012). "By engineering NK-Exos to overexpress NKG2D and IL24, these exosomes can simultaneously enhance the recognition of tumor cells via NKG2D–ligand interactions and induce apoptosis through IL24-mediated signaling pathways." (PMID 40076725, 2025). "The findings from this study provide significant insights into the anti-tumor effects of NK-Exo, particularly those overexpressing NKG2D and IL24." (PMID 40076725, 2025). "Given the potent anti-tumor properties of both NKG2D and IL24, their combination with NK-Exos presents a novel and promising strategy for cancer therapy." (PMID 40076725, 2025). "This research delves into the boosted anti-tumor potency of NK-Exos that has been genetically enhanced to overexpress NKG2D, a vital activating receptor, along with interleukin-24 (IL24), a cytokine renowned for its selective suppressive impact on tumor cells." (PMID 40076725, 2025). "IL-24 also modulates the TME by suppressing angiogenesis and reducing immunosuppressive factors, contributing to a more favorable immune landscape for tumor control." (PMID 40806452, 2025). "Accordingly, the combinatory treatment with IL-24 plus the anti-VEGF inhibitor, bevacizumab, determined reduced tumor growth in vivo." (PMID 40806452, 2025). "One example is a recombinant type five adenovirus containing the IL-24 gene (CNHK600-IL24), which significantly suppressed tumor growth in a nude mice model and improved survival in a metastatic model." (PMID 40303488, 2025). "In this study, to assess the anti-tumor efficacy of NK-derived exosomes that overexpress both NKG2D and IL24, the NK cells expressing NKG2D and IL24 were constructed and NK-Exos were extracted." (PMID 40076725, 2025).